APLNR (apelin receptor)
Description:
G protein-coupled receptor for peptide hormones apelin (APLN) and apelin receptor early endogenous ligand (APELA/ELA), that plays a role in the regulation of normal cardiovascular function and fluid homeostasis. When acting as apelin receptor, activates both G(i) protein pathway that inhibits adenylate cyclase activity, and the beta-arrestin pathway that promotes internalization of the receptor. APLNR/APJ also functions as mechanoreceptor that is activated by pathological stimuli in a G protein-independent fashion to induce beta-arrestin signaling, hence eliciting cardiac hypertrophy. However, the presence of apelin ligand blunts cardiac hypertrophic induction from APLNR/APJ on response to pathological stimuli. Plays a key role in early development such as gastrulation, blood vessels formation and heart morphogenesis by acting as a APELA receptor (By similarity). May promote angioblast migration toward the embryonic midline, i.e. the position of the future vessel formation, during vasculogenesis (By similarity). Promotes sinus venosus (SV)-derived endothelial cells migration into the developing heart to promote coronary blood vessel development (By similarity). Also plays a role in various processes in adults such as regulation of blood vessel formation, blood pressure, heart contractility and heart failure. (Microbial infection) Alternative coreceptor with CD4 for HIV-1 infection; may be involved in the development of AIDS dementia.
Synonyms: AGTRL1; APJ; FLJ90771; APJR; HG11
Tractability: Small molecule: a structure with a bound ligand is known; a high-quality ligand is known; it belongs to a druggable protein family. Antibody: UniProt places it where antibodies can reach, with high confidence; its Gene Ontology location is reachable by antibodies, with high confidence; UniProt predicts a signal peptide or a membrane-spanning region. PROTAC: a small molecule that binds it is known. Other modalities: a drug acting on it is in phase 2 or 3 trials.
Target class: Peptide receptor (family A GPCR); Family A G protein-coupled receptor; Short peptide receptor (family A GPCR); Membrane receptor; Neuropeptide receptor
Chemical probes: ML221, ML233
Gene: Protein-coding gene on chromosome 11 (57,233,577 to 57,237,250, reverse strand). Ensembl gene ENSG00000134817.
Subcellular location: Cell membrane
Pathways (Reactome):
Signal Transduction: G alpha (i) signalling events; Peptide ligand-binding receptors
Gene Ontology:
Molecular function: apelin receptor activity; G protein-coupled peptide receptor activity; mechanoreceptor activity; protein binding; G protein-coupled receptor activity; signaling receptor activity
Biological process: adenylate cyclase-inhibiting G protein-coupled receptor signaling pathway; apelin receptor signaling pathway; G protein-coupled receptor signaling pathway; positive regulation of angiogenesis; positive regulation of G protein-coupled receptor internalization; positive regulation of release of sequestered calcium ion into cytosol; aorta development; atrioventricular valve development; blood vessel development; coronary vasculature development; endocardial cushion formation; heart development; heart looping; negative regulation of cardiac muscle hypertrophy in response to stress; negative regulation of gene expression; positive regulation of blood vessel endothelial cell proliferation involved in sprouting angiogenesis; positive regulation of cardiac muscle hypertrophy in response to stress; regulation of gap junction assembly; regulation of gene expression; vascular associated smooth muscle cell differentiation; vasculature development; vasculogenesis; venous blood vessel development; ventricular septum morphogenesis; adult heart development; and 1 more
Cellular component: plasma membrane; membrane
Genetic constraint (gnomAD): Loss-of-function variants: 12 observed, 24.01 expected, observed/expected ratio (o/e) 0.5, 90% interval 0.32 to 0.81. The upper end of that interval is the gene's LOEUF score, 0.81, which puts it in group 3 of 6, group 1 being the genes least tolerant of losing a copy. Missense variants: 440 observed, 498.67 expected, observed/expected ratio (o/e) 0.88, 90% interval 0.81 to 0.95. Synonymous variants: 219 observed, 205.42 expected, observed/expected ratio (o/e) 1.07, 90% interval 0.95 to 1.19.
Homologues: Orthologues: chimpanzee APLNR (99% identical), macaque APLNR (99% identical), rabbit APLNR (97% identical), pig APLNR (93% identical), mouse Aplnr (91% identical), rat Aplnr (89% identical), guinea pig APLNR (85% identical), zebrafish aplnr2 (38% identical). Paralogues in human: AGTR1 (29% identical), GPR25 (27% identical), GPR15 (26% identical), AGTR2 (24% identical), BDKRB2 (24% identical), BDKRB1 (23% identical), RXFP4 (23% identical).
Diseases named in the same sentence as APLNR in open-access papers:
APLNR is named in the same sentence as 153 diseases in open-access papers, as found by Europe PMC text mining. Sharing a sentence is not in itself a finding about the gene and the disease. The quoted sentences say what the papers report.
Hypertension (32 papers, 2012 to 2025). The presence of chronic increased pressure in the systemic arterial system. "Numerous studies have shown that APLN/APLNR polymorphisms are associated with the risk of several diseases such as hypertension, CAD, and diabetes mellitus." (PMID 32849850, 2020). "Some variants in the APLNR gene correlate with the risk of arterial hypertension." (PMID 37888112, 2023). "Some variants in the APLNR gene correlate with the risk of hypertension." (PMID 36983642, 2023). "However, the strongest signal on chromosome 11 was a relatively uncommon missense variant (rs7943508) in the APLNR gene, implicated in hypertension and some cancers." (PMID 33441574, 2021). "Several single-nucleotide polymorphisms (SNPs) in the APLNR gene have been identified and linked to cardiovascular phenotypes, including slower heart failure progression in idiopathic dilated cardiomyopathy and potential associations with hypertension or coronary artery disease." (PMID 40362262, 2025). "The multifaceted roles of the apelin/APLNR system in cardiovascular regulation and its dysregulation in hypertension and heart failure make it an attractive therapeutic target for HHD." (PMID 40362262, 2025). "Studies conducted in rats with LNAME-induced hypertension or unilateral renal artery obstruction showed a decrease in both apelin and APLNR levels in cortical and medullar kidney extracts." (PMID 39200188, 2024). "The results of the present study showed a significant difference between the expression of VEGF and APLNR in both the RC and RM at the onset of hypertension-induced renal injury (6-month-old SHRs), which was also recorded in normotensive controls." (PMID 39200188, 2024). "The apelin receptor (APJ) belongs to family A of the G protein-coupled receptors (GPCRs) and is a potential pharmacotherapeutic target for heart failure, hypertension, and other cardiovascular diseases." (PMID 28091541, 2017). "Moreover, hypertension-induced heterodimerization of APLNR and kappa-opioid receptor was normalized by apelin administration, further illustrating the intricate molecular interplay between these pathways." (PMID 40362262, 2025). "Hypertension-induced cardiac remodeling is a complex process involving multiple signaling pathways, among which the apelinergic system—comprising the apelin ligand and its receptor APLNR—plays a crucial role." (PMID 40362262, 2025). "Activating the apelin receptor with LIT01-196 may constitute a novel approach for the treatment of hypertension." (PMID 34393794, 2021). "We aimed to elucidate the role of the apelin receptor (APLNR), neuronal nitric oxide synthase (nNOS), and vascular endothelial growth factor (VEGF) in hypertension-induced renal damage." (PMID 39200188, 2024). "Overall, our findings provide valuable insight into the intricate interplay between APLNR, nNOS, and VEGF in the pathogenesis of hypertension-induced renal injury." (PMID 39200188, 2024). "To do so, we evaluated the immunohistochemical expression of the APLNR, nNOS, and VEGF and correlated it with CD, which serves as a reliable quantitative parameter for assessing angiogenesis and hypertension-induced renal damage." (PMID 39200188, 2024). "The present study explored the immunohistochemical localization of APLNR, nNOS, and VEGF in the kidney of SHRs, as well as their potential interactions in the context of hypertension-induced renal damage." (PMID 39200188, 2024). "Our study strongly suggests that APLNR, nNOS, and VEGF are essential components of a sophisticated compensatory vascular mechanism aiming to restore VEGF levels and adequate renal perfusion in order to mitigate hypertension-induced renal damage." (PMID 39200188, 2024). "Additionally, the apelin receptor (APJ), a widely expressed G protein-coupled receptor, holds promise as a therapeutic target for peptide analogs in treating myocardial infarction and hypertension-induced heart failure." (PMID 40860357, 2025).
Hypertension (continued). "Building upon these findings, we hypothesize that alterations in APLNR expression and, indirectly, the apelinergic system might play a crucial role in regulating the signaling of nNOS and VEGF in the context of hypertension-induced depletion of renal angiogenesis." (PMID 39200188, 2024).
heart failure (26 papers, 2012 to 2025). Inability of the heart to pump blood at an adequate rate to meet tissue metabolic requirements. "The pathway of apelin and its apelin receptor (APJ) was implicated in the pathogenesis of heart failure in animal models, but a similar role in humans is unknown." (PMID 25993436, 2015). "The objective was to recapitulate the reduction of the apelin receptor observed in heart failure patients." (PMID 36239923, 2023). "Knockdown in 3D engineered heart tissues recapitulated the phenotype of apelin receptor down-regulation in a failing heart, providing a potential platform for modelling heart failure and testing novel therapeutic strategies." (PMID 36239923, 2023). "There is strong evidence for benefit of apelin receptor agonists in pulmonary arterial hypertension and chronic kidney disease with further potential in heart failure as apelin promotes inotropy and has anti-fibrotic and antiplatelet actions." (PMID 37956047, 2023). "Targeting APLNR helps prevent heart failure resulting from pressure overload via suppression of angiotensin-converting enzyme expression and pathogenic angiotensin II signaling." (PMID 32708358, 2020). "It is especially interesting that the positive inotropic effect of the peptide is preserved in the failing heart, although the apelin–apelin receptor system is chronically downregulated in heart failure." (PMID 24695532, 2014). "Together, these results support a pivotal role of the apelin receptor in cardiomyocyte development and physiological function, as well as having the potential for using this platform to screen for novel therapeutic agents for the treatment of heart failure." (PMID 36239923, 2023). "Future comprehensive genetic analysis by genotyping and analyzing more SNPs in the APLNR gene and other genes in the apelin/APJ pathway as well as haplotype analysis may further define the role of the apelin/APJ pathway in the pathology of heart failure." (PMID 25993436, 2015).
diabetes (21 papers, 2012 to 2025). "APLNR signaling is associated with several pathologies, including ischemic stroke, cardiopathy, obesity, diabetes, and cancer, suggesting that APLNR function may have a crucial role in multiple physiological systems." (PMID 37965346, 2023). "Our study therefore reinforces this by demonstrating that the beneficial effects of these analogues in diet-induced obesity mice model were mediated via the apelin receptor, making it a novel therapeutic target in diabetes." (PMID 31472173, 2019). "Studies on APLNR gene variants have not detected any associations with diabetes mellitus or obesity." (PMID 36983642, 2023). "Elabela, a new peptide that acts via Apelin receptor, has similar functions as Apelin, providing beneficial effects on body fluid homeostasis, cardiovascular health and renal insufficiency, as well as potentially beneficial effects on metabolism and diabetes." (PMID 33244875, 2021). "Type 2 diabetes mellitus (T2DM) is significantly influenced by the Elabela hormone, Elabela has been discovered to be a new endogenous apelin receptor (APJ) ligand." (PMID 41179537, 2025).
Obesity (20 papers, 2011 to 2025). Accumulation of substantial excess body fat. "The apelin gene (APLN) is localised on the X chromosome at Xq25-q26.1, a region close to a susceptibility locus for obesity that was identified by linkage mapping in the African Americans, while the apelin receptor gene (APLNR) is located on chromosome 11q12." (PMID 32998691, 2020). "Therefore, our study was interested in examining links of the APLNR G212A polymorphism with apelin concentration and obesity phenotypes among Thai children." (PMID 32998691, 2020). "The purposes of this study were to examine apelin concentrations and anthropometric-cardiometabolic parameters in obese and non-obese children and to identify associations of APLN T-1860C and APLNR G212A polymorphisms with apelin levels and obesity among Thai children." (PMID 32998691, 2020). "However, relatively few studies have observed a correlation between APLNR G212A polymorphism with circulating apelin level and obesity phenotypes." (PMID 32998691, 2020). "Therefore, the present study aimed to examine concentrations of apelin and anthropometric-cardiometabolic parameters in obese and non-obese children and to search for associations of APLN T-1860C and APLNR G212A polymorphisms with apelin levels and obesity among Thai children." (PMID 32998691, 2020). "Although molecular studies on APLN and APLNR genes have been performed, the relationships of these genes with obesity remain limited, especially in children." (PMID 32998691, 2020). "Apelin regulates body fluid homeostasis and cardiovascular functions through the apelin receptor, APJ, and the level of plasma apelin markedly increases in obesity that is associated with insulin resistance and hyperinsulinemia." (PMID 21437254, 2011). "As for patients with COPD, the Activin A Receptor Type 2B (ACVR2B) and Transforming Growth Factor Beta 1 (TGFβ1), which were the key modulators of BMPR2 pathway, were significantly downregulated, as well as the obesity-related gene Apelin Receptor Early Endogenous Ligand (APELA)." (PMID 37886639, 2023). "However, the current findings among Thai children found that neither apelin concentration nor obesity phenotypes were related to the APLNR G212A polymorphism." (PMID 32998691, 2020). "The interaction between APLNR, VEGF, leptin, and DNA methylation creates a complex network in the placenta that influences the development and progression of GDM and obesity." (PMID 41302116, 2025). "To explore the expression levels of apelin/APLNR in MASLD mice, we utilized a high-fat diet (HFD)-induced obesity mouse model, which disrupts the balance between lipid synthesis and degradation, leading to lipid accumulation and cytotoxicity in hepatocytes." (PMID 39744169, 2025). "Therefore, our findings suggest that APLNR G212A polymorphism may not be involved in circulating apelin concentration and obesity among Thai children." (PMID 32998691, 2020). "The functional role of the APLNR G212A polymorphism at the 5′ untranslated region has not yet been identified, and the fact that the presence of the A allele is associated with lower cardiovascular risk in an Italian population consequently suggests that it may be profitable in obesity." (PMID 32998691, 2020). "Obesity has a similar effect, but the decrease in leptin and APLNR expression was not significant." (PMID 41302116, 2025). "Finally, we did not analyse the entire APLN and APLNR genes with obesity." (PMID 32998691, 2020).
pulmonary arterial hypertension (15 papers, 2015 to 2026). Pulmonary arterial hypertension (PAH) is a group of diseases characterized by mean pulmonary artery pressure >20 mmHg and elevated pulmonary arterial resistance leading to right heart failure. "The Apelin/Elabela-APLNR signaling has been implicated in pulmonary arterial hypertension, one of the major complications of SSc." (PMID 30327649, 2018). "The apelin receptor, therefore, presents a highly tractable drug target for cardiovascular disorders characterised by high blood pressure and a failing heart, such as pulmonary arterial hypertension (PAH)." (PMID 36967803, 2023). "Signaling through the apelin receptor is beneficial for a number of diseases including pulmonary arterial hypertension." (PMID 33716722, 2020). "Much of the current interest in apelin and the cardiovascular system has focussed on the potential therapeutic benefit of targeting the apelin receptor in pulmonary arterial hypertension (PAH) and HF." (PMID 26143239, 2015). "It greatly enhances the spatiotemporal signaling potential through the apelin receptor and how it is modulated in disease, with evidence that ELA, like apelin, is downregulated in human pulmonary arterial hypertension and animal models of the disease already demonstrated." (PMID 31492821, 2019). "Apelin is an endogenous vasodilatory and inotropic peptide that is down‐regulated in human pulmonary arterial hypertension, although the density of the apelin receptor is not significantly attenuated." (PMID 30710493, 2019). "Apelin peptide (but not the target receptor) is significantly reduced in cardiovascular disease such as heart failure and pulmonary arterial hypertension (PAH), where the therapeutic hypothesis is that apelin receptor agonists are needed to replace the missing endogenous peptide." (PMID 31492821, 2019).
atherosclerosis (13 papers, 2012 to 2025). A disease characterized by the build-up of fatty material and calcium deposition in the arterial wall resulting in partial or complete occlusion of the arterial lumen. "Previous functional research identified an association between the apelin receptor and apelin with atherosclerosis." (PMID 29296197, 2017). "In a mouse model, APLNR was found to be associated with atherosclerosis." (PMID 29296197, 2017). "Through further differential analysis and screening using machine learning algorithms, APLNR, PCDH12, PODXL, SLC40A1, TM4SF18, and TNFRSF25 were identified as key diagnostic genes for atherosclerosis." (PMID 40070840, 2025). "The ROC curve was employed to assess the predictive potential of these key gene markers in atherosclerosis, revealing that the AUC values for APLNR, PCDH12, PODXL, SLC40A1, TM4SF18, and TNFRSF25 were 0.763, 0.859, 0.780, 0.807, 0.792, and 0.848, respectively." (PMID 40070840, 2025). "We determined that APLNR, PCDH12, PODXL, SLC40A1, TM4SF18, and TNFRSF25 are key genes associated with lipid metabolism in samples affected by atherosclerosis." (PMID 40070840, 2025). "In our study, we identified APLNR, PCDH12, PODXL, SLC40A1, TM4SF18, and TNFRSF25 as the most relevant genes associated with lipid metabolism and atherosclerosis, highlighting their potential as diagnostic and immune markers." (PMID 40070840, 2025). "Our study employed various machine learning algorithms to identify that APLNR, PCDH12, PODXL, SLC40A1, TM4SF18, and TNFRSF25, among the lipid metabolism genes, can serve as diagnostic markers in patients with atherosclerosis and are associated with atherosclerotic immune infiltration." (PMID 40070840, 2025). "Through our investigation, we discerned the crucial functions of APLNR, PCDH12, PODXL, SLC40A1, TM4SF18, and TNFRSF25 within the framework of atherosclerosis." (PMID 40070840, 2025). "Conversely, downregulation of FABP4 by apelin/apelin receptor (APLNR)-mediated Forkhead box O1 (FOXO1) suppression in ECs limits excessive FA transport and tissue accumulation, contributing to atheroprotecton against vascular diseases such as atherosclerosis." (PMID 40890841, 2025).